CXCR6 (C-X-C motif chemokine receptor 6)
Diseases named in the same sentence as CXCR6 in open-access papers (continued):
Sharing a sentence is not in itself a finding about the gene and the disease.
metabolic disease (1 paper, 2021). A congenital disorder (due to inherited enzyme abnormality) or acquired (due to failure of a metabolically important organ) disorder resulting from an abnormal metabolic process. "At the same time, Dudek, M. et al55 revealed that liver‐resident CXCR6+ CD8+ T cells are rendered auto‐aggressive through defined, non‐redundant sequential activation steps in immune‐mediated metabolic diseases such as NASH, causing a chronic liver damage." (PMID 34469018, 2021).
CXCR6 also shares sentences with these, for which no sentence is quoted: Allergy (3 papers); brain tumor (3); multiple sclerosis (3); papillary thyroid cancer (3); adenocarcinoma (2); cardiovascular diseases (2); Coronary Artery Disease (2); lung disease (2); Neurologic Disease (2); non-alcoholic fatty liver disease (2); rectal cancer (2); renal carcinoma (2); schwannoma (2); Atrophy (1); biliary atresia (1); bone resorption disease (1); brain cancer (1); Chlamydia infection (1); chronic prostatitis (1); cognitive decline (1); colorectal adenocarcinoma (1); diffuse large B-cell lymphoma (1); End Stage Liver Disease (1); epithelial ovarian cancer (1); esophagus tumors (1); Ewing sarcoma family tumor (1); glomerulonephritis (1); head and neck cancer (1); Hepatic steatosis (1); Immunodeficiency (1).
A further 18 diseases each share a sentence with CXCR6 in 1 paper.